BRIX1 (biogenesis of ribosomes BRX1)
Description:
Required for biogenesis of the 60S ribosomal subunit.
Synonyms: BRIX; BXDC2; FLJ11100
Tractability: Small molecule: a structure with a bound ligand is known. PROTAC: UniProt records ubiquitination sites on it; ubiquitination databases record sites on it; its protein half-life has been measured.
Gene: Protein-coding gene on chromosome 5 (34,915,273 to 34,926,622, forward strand). Ensembl gene ENSG00000113460.
Subcellular location: Nucleus, nucleolus
Subcellular location (Human Protein Atlas): Mitotic chromosome; Nucleoli
Gene Ontology:
Molecular function: protein binding; RNA binding; rRNA binding
Biological process: rRNA processing
Cellular component: chromosome; nucleolus
Genetic constraint (gnomAD): Loss-of-function variants: 6 observed, 18.91 expected, observed/expected ratio (o/e) 0.32, 90% interval 0.17 to 0.63. The upper end of that interval is the gene's LOEUF score, 0.63, which puts it in group 2 of 6, group 1 being the genes least tolerant of losing a copy. Missense variants: 275 observed, 269.2 expected, observed/expected ratio (o/e) 1.02, 90% interval 0.93 to 1.13. Synonymous variants: 103 observed, 89.88 expected, observed/expected ratio (o/e) 1.15, 90% interval 0.98 to 1.35.
Homologues: Orthologues: chimpanzee BRIX1 (99% identical), macaque BRIX1 (98% identical), pig BRIX1 (94% identical), rabbit BRIX1 (93% identical), dog BRIX1 (92% identical), mouse Brix1 (92% identical), rat Brix1 (92% identical), guinea pig BRIX1 (88% identical), tropical clawed frog brix1 (70% identical), zebrafish bxdc2 (63% identical), Drosophila melanogaster CG11583 (46% identical), Caenorhabditis elegans K12H4.3 (39% identical).
Diseases named in the same sentence as BRIX1 in open-access papers:
BRIX1 is named in the same sentence as 17 diseases in open-access papers, as found by Europe PMC text mining. Sharing a sentence is not in itself a finding about the gene and the disease. The quoted sentences say what the papers report.
colorectal cancer (2 papers, 2024). A primary or metastatic malignant neoplasm that affects the colon or rectum. "Our results also showed that BRIX1 was highly expressed in breast and colorectal cancers and higher levels of BRIX1 correlated with worse prognoses." (PMID 39475053, 2024). "Considering that BRIX1 was necessary for the survival and proliferation of breast and colorectal cancer cells, we investigated the clinical significance of BRIX1 in these two types of cancer." (PMID 39475053, 2024). "By evaluating the expression of BRIX1 and p21 in 62 colorectal cancer samples, we found that elevated levels of BRIX1 were associated with advanced TNM stages and a poor prognosis, while high levels of p21 correlated with a favorable prognosis." (PMID 39475053, 2024). "A strategy employing exosomes engineered to target BRIX1 is demonstrated to effectively suppress colorectal cancer both in vitro and in vivo." (PMID 39475053, 2024). "Furthermore, both univariate and multivariate analyses indicated that BRIX1 served as a prognostic factor in colorectal cancer." (PMID 39475053, 2024). "Also, our analysis revealed an inverse correlation between the expression of BRIX1 and p21 in colorectal cancer." (PMID 39475053, 2024).
breast carcinoma (1 paper, 2024). "In addition, immunohistochemistry (IHC) analysis of 91 breast cancer tissues revealed that higher expression of BRIX1 was significantly associated with higher tumor/node/metastasis (TNM) stages and worse overall survival of patients." (PMID 39475053, 2024). "Our results showed that the protein and mRNA levels of BRIX1 were elevated in breast cancer tissues compared to normal tissues." (PMID 39475053, 2024). "To explore the potential signaling pathways that are regulated by BRIX1, we performed an RNA‐sequencing (RNA‐seq) analysis by depleting BRIX1 in CAL‐51 breast cancer cells." (PMID 39475053, 2024). "In conclusion, our study identifies BRIX1 as an oncoprotein that is overexpressed in colorectal and breast cancers, correlating with unfavorable prognoses." (PMID 39475053, 2024). "First, we assessed the expression of BRIX1 in breast cancer and matched normal tissues by IB and RT‐qPCR analyses." (PMID 39475053, 2024). "Moreover, univariate and multivariate Cox regression analysis further confirmed that high expression of BRIX1 was a poor prognostic factor in breast cancer." (PMID 39475053, 2024).
colorectal tumors (1 paper, 2024). "Altogether, these results demonstrate that targeted inhibition of BRIX1 via iRGD‐modified exosomes can effectively suppress the growth of colorectal tumors and enhance their sensitivity to chemotherapy." (PMID 39475053, 2024).
fibrosarcoma (1 paper, 2025). A malignant mesenchymal fibroblastic neoplasm affecting the soft tissue and bone. "Notably, WDR75 showed the strongest association with rapidly accelerated fibrosarcoma (RAF), while DNTTIP2 and BRIX1 were most closely related to CTLA4." (PMID 40577282, 2025).
gastric cancer (1 paper, 2019). A primary or metastatic malignant neoplasm involving the stomach. "BRIX1 (ribosomal biogenesis protein BRX1) is a protein-coding gene associated with the gastric cancer network pathway and neural development of the chicken brain." (PMID 31117270, 2019).
psoriasis (1 paper, 2022). An autoimmune condition characterized by red, well-delineated plaques with silvery scales that are usually on the extensor surfaces and scalp. "BRIX1 is a new potential target in psoriasis and diffuse superficial actinic sweat keratosis." (PMID 35571562, 2022).
cancer (5 papers, 2021 to 2025). A tumor composed of atypical neoplastic, often pleomorphic cells that invade other tissues. "Both mRNA and protein levels of BRIX1 were upregulated in various cancerous tissues compared to normal tissues, and higher levels of BRIX1 were associated with worse prognoses in different types of cancer." (PMID 39475053, 2024). "Based on our findings, targeting BRIX1 might be a potential strategy for cancer therapy by triggering nucleolar stress." (PMID 39475053, 2024). "Next, we tested whether ectopic BRIX1 promoted the survival and growth of cancer cells under nucleolar stress." (PMID 39475053, 2024). "Our results revealed that overexpression of BRIX1 significantly increased the proliferation and colony formation, while reduced apoptosis of cancer cells when treated with a low dose of Act D. In addition, ectopic BRIX1 promoted the migration of cancer cells." (PMID 39475053, 2024). "Moreover, engineered exosomes are developed, which are surface‐decorated with iRGD, a tumor‐homing peptide, and loaded with siRNAs specific to BRIX1, for the treatment of cancer." (PMID 39475053, 2024). "Finally, our results demonstrate that utilizing an exosome‐based delivery system loaded with siRNA specific to BRIX1 could be a promising approach for cancer treatment." (PMID 39475053, 2024). "Moreover, the migration of cancer cells was also dramatically inhibited by depleting BRIX1." (PMID 39475053, 2024). "The co‐IP assays revealed that BRIX1 bound to both RPL5 and RPL11 in cancer cells when treated with Act D." (PMID 39475053, 2024). "In addition, we also observed that genes contributing to cancer cell stemness, such as CDKN3, BRIX1, TBCA, TMX2, and others, were highly expressed in the Luminal A DAB2IP-low tumors compared with the DAB2IP-high Luminal A tumors." (PMID 39418101, 2024). "While the endogenous interaction between BRIX1 and BOP1 was observed in cancer cells, the protein levels of BOP1 were not affected by knocking down BRIX1." (PMID 39475053, 2024).
tumor (4 papers, 2020 to 2024). "Moreover, we determined the role of BRIX1 in vivo by establishing a xenograft tumor model." (PMID 39475053, 2024).
BRIX1 also shares sentences with these, for which no sentence is quoted: bladder cancer (1 paper); bladder tumors (1); lung adenocarcinoma (1); lung carcinoma (1); non-small cell lung carcinoma (1); ovarian carcinoma (1); pancreatic cancer (1); tongue cancer (1); urothelial neoplasm (1).